SPATA31A5 (SPATA31 subfamily A member 5)
Description:
May play a role in spermatogenesis.
Synonyms: FAM75A5; OTTHUMG00000013204
Tractability: Antibody: UniProt predicts a signal peptide or a membrane-spanning region.
Gene: Protein-coding gene on chromosome 9 (60,914,407 to 60,920,653, forward strand). Ensembl gene ENSG00000276581.
Subcellular location: Membrane
Subcellular location (Human Protein Atlas): Acrosome; Equatorial segment
Gene Ontology:
Cellular component: membrane
Homologues: Orthologues: mouse Spata31 (27% identical), rat Spata31 (27% identical). Paralogues in human: SPATA31A7 (99% identical), SPATA31A3 (99% identical), SPATA31A1 (98% identical), SPATA31A6 (98% identical), SPATA31C1 (76% identical), SPATA31C2 (73% identical), SPATA31E1 (34% identical), SPATA31D1 (27% identical), SPATA31D3 (18% identical), SPATA31D4 (18% identical), SPATA31F1 (18% identical), SPATA31F3 (2% identical).